TLN1 (talin 1)
Diseases named in the same sentence as TLN1 in open-access papers (continued):
Sharing a sentence is not in itself a finding about the gene and the disease.
dilated cardiomyopathy (3 papers, 2020 to 2025). Cardiomyopathy which is characterized by dilation and contractile dysfunction of the left and right ventricles. "Ankrd1 binds to talin-1 in cardiac muscle cells, and Ankrd1 mutations in dilated cardiomyopathy result in a loss of this binding." (PMID 40362467, 2025). "Asb2 was also demonstrated to ubiquitylate talin-1 (Tln1), a protein that is together with talin-2 required for myoblast fusion and sarcomere assembly of skeletal muscles, and whose loss results in costameric instability and dilated cardiomyopathy in hearts." (PMID 33114658, 2020).
gastric cancer (3 papers, 2016 to 2025). A primary or metastatic malignant neoplasm involving the stomach. "It has been found that the AC129507.1/(FLNA, TLN1) signaling axis affects the prognosis of gastric cancer through the FOCAL ADHESION pathway." (PMID 40104507, 2025). "We found that TLN1 may influence prognosis of gastric cancer through the PTK2-PXN-VCL-E-Cadherin-CAPN2-MAPK1 signaling pathway." (PMID 40104507, 2025).
kidney failure (3 papers, 2016 to 2020). An acute or chronic condition that is characterized by the inability of the kidneys to adequately filter the blood. "This ability largely depends on its intimate relationship with talin, which also is required to maintain glomerular barrier integrity; podocyte-specific KO of talin 1 causes severe glomerular dysfunction and early kidney failure." (PMID 29241625, 2018).
lung adenocarcinoma (3 papers, 2020 to 2023). A carcinoma that arises from the lung and is characterized by the presence of malignant glandular epithelial cells. "The search revealed that lung adenocarcinoma patients with higher talin-1 expression show poorer overall survival than those with lower talin-1 expression." (PMID 32742451, 2020). "Moreover, TLN1 levels were almost three times higher (p-value = 0.00114) in patients with lung squamous cell carcinoma (SqC) (84.4 ± 27.4 nM) than in lung adenocarcinoma (LAC) patients (29.5 ± 12.2 nM)." (PMID 34684727, 2021).
lymph node metastasis (3 papers, 2020 to 2023). "In the exosomes from patients with lymph node metastasis, 697 differentially expressed proteins were identified, and overexpressed proteins included SRC, TLN1, integrin β2 subunit, and CAPNS1." (PMID 35406748, 2022).
Sepsis (3 papers, 2019 to 2025). Sepsis is defined as life-threatening organ dysfunction caused by a dysregulated host response to infection. "We observed an upregulation of the immuno-proteasome subunit and activator PA28 (PSME1) in platelets from sepsis patients and increased processing of polyubiquitinated proteins as well as the proteasome substrate Talin-1 under conditions of sepsis." (PMID 31783490, 2019). "We measured platelet proteasome activity by fluorescent substrates, degradation of poly-ubiquitinated proteins and cleavage of the proteasome substrate Talin-1 in the presence of living E. coli strains and in platelets isolated from sepsis patients." (PMID 31783490, 2019). "Similar to the TA, gene expression of Itga7, ItgB1, Tln1, Vcl1 and Parvb was upregulated in sepsis." (PMID 41385533, 2025). "Supporting our in vitro findings, we observed increased platelet proteasome activity in platelets of patients with sepsis by fluorescent substrate cleavage as well as significantly increased cleavage of the proteasome substrate Talin-1 in the sepsis population ex vivo." (PMID 31783490, 2019). "In addition, cleavage of the proteasome substrate Talin-1, expressed as a 190 to 235 kDa ratio, was also significantly increased in platelets of sepsis patients compared to controls." (PMID 31783490, 2019). "In rAAV-sh-controls, sepsis induced upregulation across TA and EDL muscle of Ilk1 and Fermt2 and integrin-receptor-complex-related genes Itga7, ItgB1, Tln1, Lims1, Lims2, Parva (P < 0.001), whereas in SOL muscle Lims1, Lims2 and Fermt2 were not and Vcl1 (P < 0.001) was upregulated." (PMID 41385533, 2025).
skin cancer (3 papers, 2023 to 2025). "Then, we sought to determine the association of Talin-1 expression with clinicopathological characteristics and survival information of skin cancer patients." (PMID 37013489, 2023). "Similarly, THBS1, SDC4, and TLN1 have been linked to the development of metastasis and chemoresistance in skin cancer." (PMID 37510272, 2023). "Our findings from data minings through bioinformatics tools indicated dysregulation of Talin-1 in mRNA levels for skin cancer samples." (PMID 37013489, 2023). "In in-silico analysis, using the bioinformatics approach, we explored the omics data and identified significantly dysregulated gene expression of Talin-1 in skin cancers." (PMID 37013489, 2023). "The expression level of Talin-1 in skin cancer tissues was evaluated through the IHC method on TMA sections by measuring the intensity of staining, area of staining, and H-score." (PMID 37013489, 2023). "Our finding from protein evaluation also demonstrated increased expression of Talin-1 protein in skin cancer tissues compared to normal tissues." (PMID 37013489, 2023). "In this regard, this study was conducted to evaluate the potential of Talin-1 protein as a biomarker of skin cancer." (PMID 37013489, 2023). "In our study, Talin-1 staining was nearly exclusive to the cytoplasm of the skin tumor cells, confirming the previous evidence regarding the expression and function of Talin-1." (PMID 37013489, 2023). "This study investigated Talin-1 in protein levels as a potential prognosis biomarker in skin tumors." (PMID 37013489, 2023). "In the present study, at the primary search stage, comprehensive alterations in mRNA levels of Talin-1 in patients with skin cancer were analyzed using Gene Expression Profiling Interactive Analysis (GEPIA2) and Gene Expression database of Normal and Tumor tissues 2 (GENT2) databases." (PMID 37013489, 2023). "Therefore, further studies are needed on the function of Talin-1 as a potential biomarker in skin cancers as well as its prognostic value." (PMID 37013489, 2023). "Furthermore, obtained data based on GENT2 from the displayed GEO mRNA expression level of Talin-1 was significantly higher in skin cancer tissues compared to the normal skin tissues (GPL570 platform)." (PMID 37013489, 2023). "However, further studies are required to find the mechanism of action of Talin-1 in skin cancers." (PMID 37013489, 2023). "As the evidence in other cancers implies, Talin-1 may have a presumptive effect on skin cancer patients’ survival outcomes, and more studies are needed to establish the prognostic value of Talin-1 in skin cancers." (PMID 37013489, 2023). "As a critical signaling molecule of the cytoskeleton, Talin-1 regulates cadherin adhesions and may play a role in the EMT process of skin cancers." (PMID 37013489, 2023). "In conclusion, our data mining analysis indicated upregulation of Talin-1 in skin cancer patients in mRNA level in comparison with normal skin tissues." (PMID 37013489, 2023). "After analyzing of the skin cancer patient data from the TCGA database using the UCSC Xena web-based tool, a higher expression of Talin-1 was observed in skin cancer patients with metastases (n = 366) compared to primary tumor tissues (n = 102) (Welch’s t-test, p = 0.008 (t = -2.679))." (PMID 37013489, 2023).
thyroid cancer (3 papers, 2015 to 2022). "To evaluate the possible role of the cytokines IL-6 and IL-8 for the expression of selected proteins in thyroid cancer cells, we studied the impact of IL-6 and IL-8 application on Ki-67, ß1-integrin, talin-1, and beta-actin proteins in adherent ML-1 cells." (PMID 26274317, 2015). "It is known that TLN1 is involved in RPM-dependent thyroid cancer spheroid formation." (PMID 29985426, 2018). "Thus, we concluded that simulated microgravity influences the release of cytokines in follicular thyroid cancer cells, and the production of ß1-integrin and talin-1 and predicts an identical effect under real microgravity conditions." (PMID 26274317, 2015).
asthma (2 papers, 2013 to 2023). "For instance, novel IgE-related genes (CRIM1, ZNF71, TLN1, and SYNPO2) were uncovered by the only GWAS of IgE in asthma patients." (PMID 37761964, 2023). "Instead, this study identified additional candidate genes (CRIM1, ZNF71, TLN1, SYNPO2, etc.)for total serum IgE levels in asthma patients." (PMID 23967269, 2013).
bladder cancer (2 papers, 2019 to 2024). "Most disulfidoptosis genes were downregulated in multiple cancer types, including PDLIM1, TLN1, and MYH10 in lung squamous cell carcinoma (LUSC), MYL6 and DSTN in prostate adenocarcinoma (PRAD), and FLNA and ACTB in bladder cancer (BLCA)." (PMID 38862242, 2024). "In our unpublished global proteomics data of bladder carcinoma cell lines, TLN1 is >1.5-fold overexpressed in the non-type cell lines; however, its role in bladder carcinoma and whether it contributes to the “mesenchymal-like” phenotype is unclear." (PMID 31108958, 2019).
cervical cancer (2 papers, 2022 to 2023). A primary or metastatic malignant neoplasm involving the cervix. "For example, circRNA_400029 promoted cervical cancer progression by sponging miR‐1285‐3p, finally regulating TLN1 expression." (PMID 36597139, 2023).
chronic kidney disease (2 papers, 2020 to 2023). Impairment of the renal function secondary to chronic kidney damage persisting for three or more months. "The Rap1 signaling pathway and platelet activation pathway were found to be important in the development of chronic kidney disease (CKD), as were DMPs TLN1 and ACTB, as well as one malonylated site." (PMID 37833721, 2023). "Furthermore, we observed that the glomerular TLN1 expression negatively correlated with an increase of serum creatinine in the chronic kidney disease (CKD) cohort, our previous work demonstrated that TSF could significantly improve the serum creatinine level in the DKD patients." (PMID 33015191, 2020).
colitis (2 papers, 2023). Inflammation of the colon. "In summary, the results from this study indicate that myeloid talin-1 affects the number of differentiated macrophages in the colon in the context of pathogenic colitis." (PMID 38102166, 2023). "In this study, we demonstrate that epithelial expression of talin-1 helps contain C. rodentium at the luminal surface and protects against mucosal hyperplasia, neutrophil-driven colitis, and severe pathology, including death." (PMID 36951501, 2023). "In addition, myeloid-derived talin-1 does not contribute to DSS colitis." (PMID 38102166, 2023).
congenital cataracts (2 papers, 2024 to 2025). "The de novo talin-1 variant P229S we identified recently was from a patient with a complex phenotype, including thrombocytopenia, leukopenia, congenital cataracts, eczema, and intermittent sinusitis, otitis media and bronchitis." (PMID 40960860, 2025). "Here, we report a patient carrying a missense variant, L353F, in the talin-1 head which is associated with a complex set of symptoms, including skin lesions, blood cell abnormalities, and congenital cataracts." (PMID 40960860, 2025). "In our previous studies, we explored the cellular consequences of cancer-associated somatic talin-1 mutations and a unique talin-1 variant, P229S, which was found to be associated with diverse symptoms, including thrombocytopenia, lymphopenia, congenital cataracts, and skin changes." (PMID 39163585, 2024).
heart failure (2 papers, 2023 to 2025). Inability of the heart to pump blood at an adequate rate to meet tissue metabolic requirements. "Compared to the Control group, the expression of Tln1 and TGFβ2 was significantly increased in the human patient heart failure group (SFigure 1)." (PMID 40819162, 2025). "We also validated Tln1 and TGFβ2 using human patient heart failure datasets(GSE116250)." (PMID 40819162, 2025).
infectious colitis (2 papers, 2023). A viral or bacterial infectious process affecting the large intestine. "Collectively, our data demonstrate that loss of macrophage talin-1 is protective in the C. rodentium model of infectious colitis through a non-cell-autonomous manner and suggest that talin-1 is a promising target to limit the recruitment of macrophages during infectious colitis." (PMID 38102166, 2023). "Thus, we demonstrate that talin-1 plays a role in the manifestation of infectious colitis by increasing mucosal macrophages, with an effect that is independent of macrophage activation." (PMID 38102166, 2023). "Taken together, these findings implicate talin-1 as a regulator of CEC response and T cell recruitment during infectious colitis that restricts C. rodentium pathogenesis." (PMID 36951501, 2023).
metastatic prostate carcinoma (2 papers, 2015 to 2020). A carcinoma that arises from the prostate gland and has spread to other anatomic sites. "TLN-1 is upregulated in primary and metastatic prostate cancer compared to the normal prostate gland and its downregulation led to a reduction of metastatic ability in vivo." (PMID 32545553, 2020).
multiple sclerosis (2 papers, 2018 to 2025). A progressive autoimmune disorder affecting the central nervous system resulting in demyelination. "As a next step, we investigated whether EZH2 and TLN1 expression was modulated by commonly used multiple sclerosis therapies." (PMID 30367633, 2018). "Further stratification of the multiple sclerosis group into the different clinical forms revealed significantly decreased gene expression levels of EZH2, TLN1, and VAV1 in PBMC from RRMS, SPMS, and PPMS patients compared to HC." (PMID 30367633, 2018). "Expression levels for EZH2, TLN1, and VAV1 were significantly decreased in PBMC from the whole multiple sclerosis group compared to controls." (PMID 30367633, 2018).
prostate tumor (2 papers, 2019 to 2020). "Furthermore, the expression of TLN-1 has been reported as being significantly high in poorly differentiated prostate tumors and in cells with highly metastatic potential." (PMID 32545553, 2020). "Previous publications indicate that all four of the biomarkers tested in the current work (PAK7, TARDBP, TLN1 and CALD1) are highly expressed in prostate tumor cells as compared with non-cancerous prostate tissues." (PMID 31404106, 2019).
squamous cell carcinoma (2 papers, 2023 to 2026). A carcinoma arising from squamous epithelial cells. "In contrast, Talin-1 expression was reduced in malignancy and did not demonstrate statistical significance in adenocarcinoma (χ2 = 2.11, p = 0.146), squamous cell carcinoma (χ2 = 0.01, p = 0.912), or NSCLC overall (χ2 = 1.12, p = 0.289)." (PMID 41994707, 2026).
Systemic capillary leak syndrome (2 papers, 2024). Systemic capillary leak syndrome (SCLS) is a severe systemic disease due to increased capillary permeability, characterized by episodes of hypotension, edema and hypovolemia. "Evidence of this bridging role between cell–cell and cell-ECM adhesions is evident from the identification of a mutation in the talin-1 (TLN1) gene that gives rise to systemic capillary leak syndrome (SCLS)." (PMID 39163585, 2024).
AIDS (1 paper, 2010). A syndrome resulting from the acquired deficiency of cellular immunity caused by the human immunodeficiency virus (HIV). "For example, the host protein interaction net such as VCL - TLN1 - actin, cytoplasmic 2(ACTG1) - FLNA was found to interact with nef and pol (HIV function proteins), and be substantially up-regulated in HIV/AIDS patients." (PMID 20222986, 2010).
anaphylaxis (1 paper, 2022). An acute hypersensitivity reaction that occurs from exposure to an allergen. "Six genes (GATA1 (P‐value = 2.52 × 10−2), SELP (P‐value = 1.86 × 10−2), MPL (P‐value = 2.72 × 10−2), F13A1 (P‐value = 1.62 × 10−2), SPARC (P‐value = 2.97 × 10−2) and TLN1 (P‐value = 6.13 × 10−3)) were significantly downregulated in anaphylaxis patients compared with healthy controls." (PMID 36583159, 2022). "Our validation work demonstrated the downregulation of six platelet‐related genes (TLN1, GATA1, SELP, SPARC, MPL and F13A1) in anaphylaxis patients compared with healthy controls." (PMID 36583159, 2022). "One gene (TLN1 (adjusted P‐value = 1.29 × 10−2)) was also significantly downregulated in moderate anaphylaxis patients who did not receive adrenaline before ED arrival compared with healthy controls." (PMID 36583159, 2022). "TLN1 downregulation was observed in severe and moderate anaphylaxis irrespective of treatment with adrenaline, suggesting downregulation of this gene is independent of treatment and severity." (PMID 36583159, 2022). "One gene (TLN1 (adjusted P‐value = 1.29 × 10−2)) was significantly downregulated in moderate anaphylaxis patients who did not receive adrenaline before ED arrival, compared with healthy controls." (PMID 36583159, 2022). "No role of TLN1 in anaphylaxis has previously been described." (PMID 36583159, 2022). "Seven genes (TLN1, GATA1, SELP, GP1BA, MPL, F13A1 and SPARC) were also downregulated in patients with severe anaphylaxis who did not receive adrenaline before ED arrival, compared with healthy controls." (PMID 36583159, 2022).
aortic aneurysm (1 paper, 2017). A ruptured aneurysm located in the wall of the proximal portion of the descending aorta proceeding from the arch of the aorta. "In addition, further experiments to reveal whether the expressive discrepancy of Talin-1 exists in other vascular diseases such as aortic aneurysm will be a focus of future study." (PMID 28637452, 2017).
arterial diseases (1 paper, 2024). "Alterations in the expression of TLN1 in smooth muscle cells have been associated with major risk of human arterial diseases, confirming the importance of talin 1 in vascular integrity." (PMID 39654947, 2024).
Arterial thrombosis (1 paper, 2020). The formation of a blood clot inside an artery. "Talin-1 was reported to increase platelet adhesion and aggregation, while Talin-1 deficiency caused severe hemostatic defects and resistance to arterial thrombosis." (PMID 32566035, 2020).
benign ovarian tumors (1 paper, 2023). "Therefore, the present study was designed to evaluate the expression pattern, clinical significance, and prognostic value of talin-1 expression with various clinicopathological parameters by applying the IHC technique on TMA sections from OSC, benign ovarian tumors, and normal ovarian samples." (PMID 37942198, 2023).
benign prostatic hyperplasia (1 paper, 2026). A non-cancerous nodular enlargement of the prostate gland. "TLN1 expression was further validated in clinical prostate tissue samples (59 PCa, 17 benign prostatic hyperplasia) via immunohistochemistry, qPCR, and Western blot." (PMID 42112334, 2026).
carotid atherosclerosis (1 paper, 2019). A thickening and loss of elasticity of the walls of carotid arteries that occur with formation of atherosclerotic plaques. "Second, the stability of carotid atherosclerosis plaque owns a complicated mechanism, and although Talin-1 plays a substantial role in the regulation of plaque stability, we cannot ignore the influences of other molecular and biological factors." (PMID 31215474, 2019). "The aim of this study was to investigate the relationship between Talin-1 and stability of carotid atherosclerosis plaque and also find out the role of miRNA, as an upstream regulator, in regulating the expression level of Talin-1." (PMID 31215474, 2019).
cholangiocarcinoma (1 paper, 2024). A carcinoma that arises from the intrahepatic biliary tree (intrahepatic cholangiocarcinoma) or from the junction, or adjacent to the junction, of the right and left hepatic ducts (hilar cholangiocarcinoma). "The upregulation of talin-1 in the cholangiocarcinoma group, which is associated with the ECM, cell mobility, and adhesion, was reported to play vital roles in ECM remodelling, and attachment and metastasis were known to happen during human cholangiocarcinoma." (PMID 39189262, 2024).